RN7SL255P (RNA, 7SL, cytoplasmic 255, pseudogene)
Gene: Miscellaneous RNA gene on chromosome 5 (104,260,531 to 104,260,826, reverse strand). Ensembl gene ENSG00000239808.
Homologues: Orthologues: chimpanzee Metazoa_SRP (99% identical), macaque Metazoa_SRP (93% identical), guinea pig Metazoa_SRP (82% identical). Paralogues in human: RN7SL2 (83% identical), RN7SL1 (83% identical), RN7SL3 (81% identical), RN7SL45P (81% identical), RN7SL220P (81% identical), RN7SL122P (80% identical), RN7SL88P (80% identical), RN7SL126P (80% identical), RN7SL408P (80% identical), RN7SL47P (80% identical), RN7SL650P (80% identical), RN7SL689P (80% identical), and 705 more.